CSF2 (colony stimulating factor 2)
Description:
Cytokine that stimulates the growth and differentiation of hematopoietic precursor cells from various lineages, including granulocytes, macrophages, eosinophils and erythrocytes.
Synonyms: GM-CSF; CSF; GMCSF
Tractability: Antibody: a drug acting on it is in phase 2 or 3 trials; UniProt places it where antibodies can reach, with high confidence; its Gene Ontology location is reachable by antibodies, with high confidence; UniProt predicts a signal peptide or a membrane-spanning region. Other modalities: a drug acting on it is in phase 2 or 3 trials.
Target class: Secreted protein
Gene: Protein-coding gene on chromosome 5 (132,073,789 to 132,076,170, forward strand). Ensembl gene ENSG00000164400.
Subcellular location: Secreted
Subcellular location (Human Protein Atlas): Vesicles; Predicted to be secreted
Pathways (Reactome):
Immune System: Interleukin receptor SHC signaling; Interleukin-10 signaling; Interleukin-3, Interleukin-5 and GM-CSF signaling
Gene expression (Transcription): RUNX1 regulates transcription of genes involved in differentiation of myeloid cells
Signal Transduction: RAF/MAP kinase cascade
Gene Ontology:
Molecular function: cytokine activity; protein binding; granulocyte macrophage colony-stimulating factor receptor binding; growth factor activity
Biological process: cell surface receptor signaling pathway via JAK-STAT; cell surface receptor signaling pathway via STAT; cellular response to granulocyte macrophage colony-stimulating factor stimulus; dendritic cell differentiation; granulocyte-macrophage colony-stimulating factor signaling pathway; macrophage differentiation; myeloid dendritic cell differentiation; negative regulation of DNA-templated transcription; negative regulation of extrinsic apoptotic signaling pathway in absence of ligand; positive regulation of cell population proliferation; positive regulation of gene expression; positive regulation of interleukin-23 production; positive regulation of leukocyte proliferation; positive regulation of macrophage derived foam cell differentiation; positive regulation of podosome assembly; myeloid cell differentiation; cellular response to lipopolysaccharide; epithelial fluid transport; histamine secretion; immune response; positive regulation of cell migration; regulation of circadian sleep/wake cycle, sleep; regulation of developmental process; regulation of signal transduction; response to fluid shear stress; and 2 more
Cellular component: extracellular region; granulocyte macrophage colony-stimulating factor receptor complex; plasma membrane
Genetic constraint (gnomAD): Loss-of-function variants: 4 observed, 14.78 expected, observed/expected ratio (o/e) 0.27, 90% interval 0.13 to 0.62. The upper end of that interval is the gene's LOEUF score, 0.62, which puts it in group 2 of 6, group 1 being the genes least tolerant of losing a copy. Missense variants: 140 observed, 179.71 expected, observed/expected ratio (o/e) 0.78, 90% interval 0.68 to 0.9. Synonymous variants: 66 observed, 71.96 expected, observed/expected ratio (o/e) 0.92, 90% interval 0.75 to 1.13.
Homologues: Orthologues: chimpanzee CSF2 (99% identical), macaque CSF2 (95% identical), pig CSF2 (71% identical), guinea pig CSF2 (70% identical), dog CSF2 (69% identical), rabbit CSF2 (69% identical), rat Csf2 (63% identical), mouse Csf2 (54% identical).
Diseases named in the same sentence as CSF2 in open-access papers:
CSF2 is named in the same sentence as 722 diseases in open-access papers, as found by Europe PMC text mining. Sharing a sentence is not in itself a finding about the gene and the disease. The quoted sentences say what the papers report.
melanoma (463 papers, 1993 to 2026). A malignant, usually aggressive tumor composed of atypical, neoplastic melanocytes. "We detected higher levels of Csf2 transcripts and GM-CSF protein in the TME 5 days after RT of B16 melanoma." (PMID 40146036, 2025). "Many previous studies indicated that CSF2 produced by cancer cells is involved in the autocrine regulation of cell growth in human skin, prostate, bladder, melanoma, gastric colon and non-small-cell lung cancer cells (NSCLC)." (PMID 35463955, 2022). "Additionally, CSF2 serves as a shared target among colorectal cancer, breast cancer, Ewing’s sarcoma, melanoma, ovarian cancer, soft tissue sarcoma, and solid tumors." (PMID 41041638, 2025). "Notably, the authors observed that an early intratumoral immune cell infiltration was detected only in animals receiving recombinant murine granulocyte macrophage- colony-stimulating factor 24 h after cryoablation of xenotransplanted melanoma." (PMID 34281259, 2021). "Over-expression of CSF2 in the skin resulted in increased tumor burden in a mouse model of squamous cell carcinoma, whereas expression of its antagonist inhibits the rejection of B16 melanoma cells, suggesting a dual role of CSF2 in regulating pro- and anti-tumor immunity." (PMID 31051015, 2016). "Solid‐state antibody chip results, including 105 antibodies, showed that GC‐7 and GL‐1 affected the expression of melanoma cytokines, among which ANG, IGFBP3, CSF2, CD71, CXCL1, and MMP9 were the most significant." (PMID 38952061, 2024). "Conversely, higher expression of cytokine CSF2, which was expressed at lower levels in the PD-L1-H group, predicts worse immunotherapeutic responses for stage III/IV melanoma patients." (PMID 35145511, 2021). "Moreover, in stage IV melanoma patients with brain metastases, CCL18, CCR1, CCR4, CD274, CSF2, EGF, and PTGS2 genes were significantly over-expressed (p < 0.001, versus patients without melanoma brain metastasis)." (PMID 37091783, 2023).
COVID-19 (380 papers, 2020 to 2026). A disease caused by infection with severe acute respiratory syndrome coronavirus 2. "A third module (c) revolves around TNF and includes IL1A, IL1B, TNFSF14, TNFAIP3, and CSF2 that likely mediates the inflammatory response associated with COVID-19 progression." (PMID 35085325, 2022). "Among these genes are CD14, CSF2, and CXCL10, which are linked to COVID-19 related cytokine storm (CD14 and CXCL10) and acute respiratory syndrome (ARDS) (CSF2/GM-CSF)." (PMID 36980301, 2023). "A cohort study demonstrated a positive correlation between CSF2 and disease severity in COVID-19 patients." (PMID 36034710, 2022). "Molecular docking suggested that active ingredients (including: licopyranocoumarin, Glycyrol and 3-3-Oxopropanoic acid) in LHQW played a role in treating COVID-19 by acting on CSF2, CXCL8, CCR5, NLRP3, IFNG and TNF." (PMID 36506032, 2022). "High levels of CSF2 are found in the blood of severe COVID-19 patients, so CSF2 is a proxy for excessive inflammation in severe COVID-19 patients." (PMID 36034710, 2022). "These identified cytokines, such as IL-6, CXCL10, and CSF2, could be potential therapeutic targets for COVID-19 damage management." (PMID 38143441, 2023). "Therefore, we believe that I-SPD and Vestitol inhibit the overexpression of CSF2 and prevent the generation of inflammatory storm and infiltration of immune cells, preventing mild and common COVID-19 patients from turning into severe ones." (PMID 36034710, 2022). "Recent reports show that a) COVID-19 patients requiring intensive care unit (ICU) have increased level of GM-CSF in China and b) drugs targeting CSF2 (GM-CSF) or its receptor (such as lenzilumab, namilumab, gimsilumab, and otilimab) are being evaluated in clinical trials with COVID-19 patients." (PMID 34376762, 2021). "Several COVID-19 clinical trials are currently focusing on inhibition of CSF2 [GM-CSF]13–15." (PMID 34376762, 2021). "The CSF2, IFNG, and IL1B expression levels were considerably lower in the COVID-19 than in the Healthy group, while those of IL6R, TLR2, TLR4, and TNF were higher." (PMID 38165854, 2024). "STRING database was used to analysis core intersection targets of LHQW and COVID-19, 13 core protein targets (including: NLRP3, TNF, CSF2, IFNG) were obtained by setting confidence degree (confidence degree>0.95)." (PMID 36506032, 2022). "An increased expression of CCL3, CCL4, CSF2, IL1B, and LTA was found in the revaccinated groups (groups 5 and 6), which in fact experienced decreased expression in severe COVID-19 patients." (PMID 36225326, 2022). "This also showed that stimulation post-BCG vaccination increased expressions of BIRC3, CCL3, CCL3L1, CCL4, CSF2, IL1B, and LTA, which in contrast, decreased in severe COVID-19." (PMID 36225326, 2022). "Pachypodol, I-SPD and Vestitol in XFBD play a role in treating COVID-19 by acting on NLRP3, CSF2, and relieve the clinical symptoms of SAR-Cov-2 infection." (PMID 36034710, 2022). "Molecular docking showed that I-SPD, Pachypodol and Vestitol in XFBD played a role in treating COVID-19 by acting on NLRP3, CSF2, and relieve the clinical symptoms of SARS-CoV-2 infection." (PMID 36034710, 2022). "Notable UPRs of COVID-19 blood included IFNA, IFNG, multiple growth factors and ligands, HIF1A, CSF1 and CSF2." (PMID 33782412, 2021). "In addition, we analyzed the possible binding between VD3 and the top 5 STAD/COVID-19 core target proteins (IL1A, IL8, ALBU, CSF2, PAI1) identified in the STRING analysis." (PMID 35571107, 2022). "Therefore, Vestitol, Pachypodol and I-SPD in Xuanfei Baidu Granules (XFBD) can effectively alleviate the clinical symptoms of COVID-19 patients through NLRP3 and CSF2." (PMID 36034710, 2022). "Therefore, Vestitol, Pachypodol and I-SPD in XFBD could effectively treat COVID-19 through NLRP3 and CSF2 and reduce the clinical symptoms of patients." (PMID 36034710, 2022). "Therefore, XFBD can effectively alleviate the clinical symptoms of COVID-19 through NLRP3 and CSF2." (PMID 36034710, 2022).
COVID-19 (continued). "Transcriptomic studies revealed remarkably enhanced expressions of CCL2, CXCL8, CSF3, CSF2, and CXCL10 in Calu-3 cells infected with SARS-CoV-2, inflammatory factors that were shown to be strongly elevated in the serum of patients with severe clinical symptoms of COVID-19." (PMID 34578229, 2021).
breast carcinoma (258 papers, 1994 to 2026). "CSF-2 encodes the cytokine GM-CSF, which has previously been shown to contribute to osteolytic bone metastasis of breast cancer by stimulating osteoclasts." (PMID 22032690, 2011). "Colony-stimulating factor 2 (CSF2) plays an important role in macrophage polarization and may be associated with poor prognosis in breast cancer and colorectal cancer." (PMID 36505439, 2022). "Finally, the high expression of CSF2 in breast cancer is associated with more CC chemokine ligand 18 (CCL18)+ macrophage infiltration, epithelial-mesenchymal transition (EMT), enhanced metastasis, and reduced patient survival." (PMID 33224886, 2020). "The overexpression of CSF2 has been associated with poor survival in patients with urothelial carcinoma and NF-κB-induced CSF2 has been shown to promote tumor metastasis in patients with lung cancer and breast cancer." (PMID 29215599, 2017). "It has been shown that breast cancer-derived CSF2 regulates Arg1 to promote an immunosuppressive TME." (PMID 39996058, 2025). "Several genes, such as IDO1, IL10 and CSF2, have been noticed to have positive correlation with HIST1H1B, and we chose CSF2 that plays critical roles in breast cancer aggressiveness to further analyze its links with HIST1H1B." (PMID 34746019, 2021). "Transient miR-200c restoration significantly increased CSF2 in mouse mammary carcinoma 66Cl-4 cells and in human TNBC SUM159PT cells." (PMID 34045467, 2021). "HIST1H1B contributes to basal-like breast cancer progression by modulating CSF2 expression, indicating a potential prognostic marker and therapeutic target for this disease." (PMID 34746019, 2021). "It remains to be determined if VEGFA and its receptor VEGFR2 and VEGFC and its receptor VEGFR3, and CSF2 and its receptor GMRA/GMRB can also serve as therapeutic targets for HER2+ breast cancer since the associations we found were modest." (PMID 26173622, 2015). "In breast cancer, CSF2 could activate the Stat3 pathway in CAA via paracrine or autocrine mechanisms, leading to increased expression and secretion of CXCL3." (PMID 39497824, 2024). "Here, we describe molecular and clinical findings related to the breast cancer cell lines SV-BR-1 (Saint Vincent’s Breast Cancer cell line 1) and SV-BR-1-GM (SV-BR-1 stably transfected with CSF2, encoding granulocyte-macrophage colony-stimulating factor (GM-CSF))." (PMID 35593340, 2022). "Thus, similar to our observations in the PDX models, it seems that while most patients exhibit a low to medium expression of CXCL1, CSF2, and IL-1β, a fraction of breast cancer patients exhibit high expression levels of these cytokines." (PMID 36551639, 2022). "Additionally, analysis of CSF2 expression in different subtypes of breast cancer showed that similar to HIST1H1B, CSF2 expression was significantly upregulated in BLBC in the TCGA dataset." (PMID 34746019, 2021). "Notably, higher CSF-2 (GM-CSF) expression in both human lung and breast cancer samples positively correlated with the cytotoxic gene signature." (PMID 32759497, 2020). "A previous study demonstrated that X-ray-irradiated senescent cancer cells could exert bystander effects, which could be mediated by autophagy in breast cancer cells by releasing CSF2 and activating the JAK2-STAT3 and AKT pathways." (PMID 30622245, 2019). "CSF2 is one of the pivotal orchestrators of basal breast cancer growth and metastasis." (PMID 28678795, 2017). "Thus, BRCA1 can contribute to the metastasis of breast cancer by influencing the expression of CSF2." (PMID 26039571, 2015). "Interestingly, HIST1H1B expression in breast cancer cells significantly promoted CSF2 expressions." (PMID 34746019, 2021). "However, in our analysis using public databases, expression of the GM-CSF-encoding gene CSF2 was not strongly correlated with that of the HuR-encoding gene ELAVL1 in the different molecular subtypes of breast cancer." (PMID 28851919, 2017).
breast carcinoma (continued). "In addition to having a pivotal role in basal breast cancer growth and metastasis, the secreted factors implicated in our previous study (IL6, CSF2, CCL5, VEGFA, and VEGFC) may also serve critical roles in other subtypes of breast cancers." (PMID 26173622, 2015). "We confirmed miR-200c-dependent upregulation of GM-CSF (CSF2), CXCL10, and CCL2 after transient transfection of miR-200c mimic compared to scramble (Scr) control in mouse mammary carcinoma and human TNBC cells." (PMID 34045467, 2021). "Our analysis revealed a positive correlation between CSF-2 (GM-CSF) and IRF8, BATF3, or CCR7 in both lung and breast cancer patient cohorts." (PMID 32759497, 2020). "Using PTPRC (CD45) gene expression as a proxy for total tumor leukocyte content, we identified a positive correlation between CSF-2 (GM-CSF) and CD45 in both lung and breast cancer patients." (PMID 32759497, 2020). "Recent evidence indicates that endogenous autophagy is correlated with the release of CSF2 and subsequent activation of the JAK2-STAT3 and AKT pathways in radiation-induced breast cancer cell." (PMID 30622245, 2019). "Further corroborating our findings, we found that mRNAs for CXCL16 as well as for IL8, CSF2, MMP9, EDN1 and CCL2 all were expressed at significantly higher levels in basal-like breast cancers as compared with luminal A tumours." (PMID 27725631, 2016). "Similar to CSF2, chemokine CCL5 is significantly overexpressed in basal over luminal breast cancer in both TCGA (p-value of 9 × 10−8) and METABRIC (p-value below 2 × 10−16)." (PMID 26173622, 2015). "VEGFA/C and CSF2 mRNA are overexpressed both basal and HER2+ breast cancer relative to luminal subtypes." (PMID 26173622, 2015). "Previously, we identified that key molecules (IL6, CSF2, CCL5, VEGFA, and VEGFC) secreted by tumor cells and stromal cells in basal breast cancer can promote metastasis." (PMID 26173622, 2015). "In TCGA, CSF2 is significantly overexpressed in basal and HER2+ breast cancer relative to luminal subtypes (p-values of 1 × 10−8 and 0.03, respectively)." (PMID 26173622, 2015). "VEGFA/C and CSF2 mRNA are overexpressed in HER2 positive breast cancer, with VEGFA and CSF2 also overexpressed in basal breast cancer." (PMID 26173622, 2015). "We have described previously in the context of bone metastasis induced by breast cancer cells that LPA through LPA1 controls the expression of IL6, IL-8, CSF2(GM-CSF), and CXCL1(Groα)." (PMID 24828490, 2014). "In addition, we found positive correlations between TSLP expression and CSF2/IL3/IL5 and differentiation genes expression in human breast cancer." (PMID 35657353, 2022). "The mRNA levels of CSF2, IL8, and TGFβ1 across the 51 breast cancer cell lines are also shown." (PMID 31293831, 2019). "Previous studies have shown that Runx factors directly regulate SOST and CSF-2 expression in other cell-types but they are not known targets of Runx2 in breast cancer cells." (PMID 22032690, 2011). "Furthermore, the s-CSF2-Ab levels were higher in patients with esophageal, colorectal, gastric, and lung cancer than in HDs but not in those with mammary cancer." (PMID 36844744, 2023). "TAMs are recruited to mammary tumors through induction of a variety of cytokines and chemokines including C-C Motif Chemokine Ligand 2 (CCL2), CCL3, CCL5, Colony Stimulating Facotor-1 (CSF-1/M-CSF), and Granulocyte-Macrophage Colony-Stimulating Factor (GM-CSF or CSF2)." (PMID 34298673, 2021). "Additionally, neither distant metastasis-free survival nor overall survival was significantly correlated with CSF2 expression in the breast cancer patients." (PMID 28851919, 2017). "In addition, ELAVL1 expression showed a strong positive correlation with CCL20 expression but not with CSF2 or CCR6 expression in breast cancer subtypes, particularly the basal-like subtype." (PMID 28851919, 2017).
breast carcinoma (continued). "We first demonstrated that expression of SOST and CSF-2 could be induced in non-metastatic MCF-7 breast cancer cells by heterologous expression of Runx2." (PMID 22032690, 2011).